SSX5 (SSX family member 5)
Description:
Could act as a modulator of transcription.
Tractability: No criterion of Open Targets' tractability assessment is met for any kind of drug.
Gene: Protein-coding gene on chromosome X (48,186,220 to 48,196,795, reverse strand). Ensembl gene ENSG00000165583.
Subcellular location (Human Protein Atlas): Nucleoli; Nucleoplasm
Gene Ontology:
Molecular function: protein binding
Biological process: regulation of DNA-templated transcription
Cellular component: nucleus
Homologues: Orthologues: mouse Ssxb9 (33% identical), mouse Ssxb8 (32% identical), mouse Ssxb15 (31% identical), mouse Ssxb6 (31% identical), mouse Ssxb1 (31% identical), mouse Ssxb10 (31% identical), mouse Ssxb3 (31% identical), rat Ssx2 (30% identical), mouse Ssxb13 (30% identical), mouse Ssxb16 (30% identical), mouse Ssxb5 (30% identical), mouse Ssxb14 (29% identical), and 3 more. Paralogues in human: SSX3 (85% identical), SSX2 (84% identical), SSX2B (84% identical), SSX7 (83% identical), SSX4 (78% identical), SSX4B (78% identical), SSX1 (77% identical).
Diseases named in the same sentence as SSX5 in open-access papers:
SSX5 is named in the same sentence as 10 diseases in open-access papers, as found by Europe PMC text mining. Sharing a sentence is not in itself a finding about the gene and the disease. The quoted sentences say what the papers report.
malignant melanoma (2 papers, 2010 to 2014). "Interestingly SSX2 was detected in almost all melanoma tissues and derived cell lines (95%) compared to SSX4 (57%), SSX1 (38%), SSX5 (33%) and SSX3 (19%) expression." (PMID 24787708, 2014).
multiple myeloma (2 papers, 2010 to 2016). "SSX1, SSX2, and SSX4 are expressed in Hodgkin's lymphoma and head and neck cancer, while SSX1, SSX2, SSX4, and SSX5 are expressed in multiple myeloma." (PMID 27276714, 2016).
prostate carcinoma (1 paper, 2016). A carcinoma that arises from epithelial cells of the prostate gland. "Prior work from our lab has demonstrated that treatment of human prostate cancer cell lines with epigenetic modifying agents (EMAs) can lead to expression of other SSX family members, including SSX3, SSX5, and SSX8." (PMID 27276714, 2016).
sarcoma (1 paper, 2018). A usually aggressive malignant neoplasm of the soft tissue or bone. "Some of the genes identified already have a well-established connection to human sarcomas, including ORAOV1, SSX5, NKX2, XAGE1, MDK and CCND1." (PMID 30093970, 2018).
synovial sarcoma (1 paper, 2025). "SSX5 belongs to the SSX gene family, which has been studied for its role in various cancers, including synovial sarcoma." (PMID 39915534, 2025).
cancer (5 papers, 2010 to 2025). A tumor composed of atypical neoplastic, often pleomorphic cells that invade other tissues. "Among the predicted nucleic acid-binding proteins there is a member (SSX-5) of a known family of cancer-testis antigens." (PMID 20975957, 2010). "SSX5 belongs to the synovial sarcoma X breakpoint proteins family and functions as transcriptional repressors eliciting spontaneous cellular and humoral immune responses in cancer patients, and thus it is potentially useful target in cancer vaccine-based immunotherapy." (PMID 34440082, 2021). "It is also notable that we identified over 10 cancer-related genes (including PHGDH, CCND1, IGFBP-2, XAGE1B/E, CYP4F22, RBM11, ORAOV1, MDK, UGT3A5, SSX5, FBL, NKX2) potentially overexpressed in EFT tumors." (PMID 30093970, 2018).
tumor (1 paper, 2010). "In this analysis they found that SSX1, 2, and 4 were expressed in 8%, 15%, and 15% of tumors, respectively, with no detection of SSX3 in any samples and detection of SSX5 in only 7 out of the total 325 tumor specimens evaluated." (PMID 20981248, 2010).
SSX5 also shares sentences with these, for which no sentence is quoted: female infertility (1 paper); head and neck cancer (1); Hodgkins lymphoma (1).